STAT3 (signal transducer and activator of transcription 3)
Diseases named in the same sentence as STAT3 in open-access papers (continued):
Sharing a sentence is not in itself a finding about the gene and the disease.
cancer (continued). "It is plausible that the ineffective modulation on STAT3 may compromise the anti-cancer effect of Erdafitinib in LUSC H520 cells." (PMID 39247610, 2024). "In recent years, NF-κB and STAT3 have garnered significant attention in various cancers." (PMID 39314630, 2024). "STAT3 is activated by tyrosine kinases, such as JAK and SRC, but the mechanism by which STAT3 maintains its activated state in cancer cells remains unclear." (PMID 38760429, 2024). "Consistently, GSEA-Hallmark analysis reveals significantly elevated enrichment scores for immune-associated and cancer-related signaling pathways, including epithelial-mesenchymal transition, Interferon-gamma response, inflammatory response, and IL6/JAK/STAT3 pathways." (PMID 38763954, 2024). "While the transcriptional interaction between RELA and STAT3 has been examined in the context of cancer, it is unclear whether this same mode of regulation exists in the context of macrophage-mediated inflammation during wound healing." (PMID 39435663, 2024). "The malfunction of the JAK/STAT3 signaling pathway is associated with cancer development and may be a promising target for new treatment; thus, understanding the role of JAK/STAT3 inhibitors may be crucial to achieve a breakthrough in cancer therapy." (PMID 38892394, 2024). "One candidate is STAT3 (signal transducer and activator of transcription 3), a ubiquitous transcription factor and multifaceted regulator of immune suppression expressed in cancers and surrounding stroma." (PMID 39886125, 2024). "Overall, STAT3 critically plays an essential role in the occurrence and growth of cancers." (PMID 38834900, 2024). "Also, STAT3 can transcriptionally regulate the expression and the activity of various ncRNAs in multiple human cancers, including CRC." (PMID 38185635, 2024). "Some studies have pointed out that the combined inhibition of the RAS/RAF/MEK/ERK and STAT3 pathways could have better anti-cancer effects." (PMID 39339184, 2024). "Thus, given the importance of STAT3 for cancer cell survival, the mechanism of constitutive STAT3 activation in cancer cells needs to be fully elucidated." (PMID 38760429, 2024). "The inhibiting STAT3 activity is considered a viable strategy for cancer treatment." (PMID 38990440, 2024). "Overactivation of STAT3, in particular, results in the heightened expression of genes that contribute to inflammation, proliferation, metastasis, and immunosuppression, collectively facilitating the onset of cancer." (PMID 39468431, 2024). "Aberrant STAT3 activation can promote oncogenesis by its cell-autonomous effects in a cancer cell." (PMID 38611065, 2024). "Its interaction with diverse molecular targets such as ALK4, MMP11, and STAT3 points out a complex network of regulatory mechanisms that may exhibit variable behaviors across different cancer types and stages." (PMID 38872210, 2024). "Interestingly, NF-κB and STAT3 share an overlapping group of cancer-related genes, indicating the crosstalk between NF-κB and the cancer-promoting JAK/STAT signaling." (PMID 39451518, 2024). "In addition, exosomal ZEB1 derived from hypoxic CSCC cells promotes SIRPα+ TAM polarization via activation of the STAT3 signalling pathway and thus facilitates immune evasion by cancer cells." (PMID 38183060, 2024). "In addition, STAT3 is an important initiator of the expression of PD-L1 and has been shown to be involved in cancer proliferation." (PMID 38203840, 2024). "STAT3 is a transcription factor that has been extensively studied due to its implication in cancer." (PMID 39000312, 2024). "Moreover, S-Nitrosylation of STAT3 at Cys259 disrupts the IL-6 induced STAT3 phosphorylation for genes required for inflammatory/immune responses and cell proliferation, including cancer." (PMID 38245798, 2024). "Several other inhibitors targeting STAT3 in multiple cancer types are currently in clinical trials." (PMID 38339245, 2024).
cancer (continued). "It was indicated that STAT3 inhibitors work well for various cancers occurring in different organs." (PMID 38834900, 2024). "Forward feedback loop of STAT3 gave malignant capacities to the cancers." (PMID 38342622, 2024). "The expression of STAT3 is ultimately upregulated, which plays a crucial role in promoting the occurrence and development of various cancers, as well as the proliferation, invasion, and migration of cancer cells." (PMID 38172648, 2024). "Moreover, phosphorylation of STAT3 signaling is involved in several cancer physiologies, including apoptosis, glycolysis, and epithelial-mesenchymal transition (EMT)." (PMID 38720012, 2024). "Specifically, the effects of the drug on CLBL-1 were largely attributed to the interference on MYC target genes expression and several signaling pathways (JAK/STAT3, mTORC1, NF-kB) involved in cellular processes such as cell survival and proliferation, which are known to be dysregulated in cancer." (PMID 38791684, 2024). "Moreover, STAT3 has also emerged as a pivotal factor in inflammation-mediated cancer, metabolism, cancer stem cells (CSCs), and the formation of pre-metastatic niches." (PMID 38786085, 2024). "Similarly, resveratrol, found in grapes, has demonstrated potential in inhibiting STAT3 activation and inducing cell cycle arrest in various cancer cell lines." (PMID 39056720, 2024). "Various cancer cells were treated with TP and each signaling inhibitor to determine whether TP affects cell viability by inhibiting STAT3 and Notch1 signaling." (PMID 38731894, 2024). "Persistent activation of STAT-3 has been observed in various cancer types, and a high level of phosphorylation of STAT-3 may be linked to a poor prognosis in cancer." (PMID 39203892, 2024). "Considering the role of STAT3 activation in the development of various cancers, STAT3 inhibition has been extensively studied as a viable target for cancer therapy, with considerable effort directed toward translating preclinical findings into the clinical trial setting." (PMID 38339245, 2024). "Additionally, targeting STAT3 through its DNA-binding domain interactions represents a novel approach for pharmacological intervention against cancers driven by constitutive STAT3 activation." (PMID 39195486, 2024). "AAG8 promotes cancer cell proliferation by activating STAT3 independently of the IL6-JAK pathway." (PMID 39659524, 2024). "Overall, this pathway seems to be of interest in cancer treatment, as it has been shown that patients of several cancer types, such as lung and prostate cancers, have a worse outcome when STAT3 and 5 are activated, while STAT1 activation is generally associated with better prognosis." (PMID 36769210, 2023). "Additionally, Embelin modulates several signal transduction pathways, including NF-κB, PI3Kinase/AKT, and STAT3, effectively inhibiting the proliferation of diverse cancer cell lines." (PMID 38234968, 2023). "STAT3 is highly expressed in many different types of cancers." (PMID 37835536, 2023). "There is a correlation between STAT3 overactivation and poor prognosis in several types of cancer." (PMID 37308913, 2023). "Inhibition or downregulation of STAT3 expression has become a main strategy for cancer therapy." (PMID 36733714, 2023). "Taken together, our data showed that STAT3 is critical in cancer immunotherapy, further illustrating that STAT3 could be a promising target for cancer therapy." (PMID 36977736, 2023). "The anti-cancer effects of LicA on SKOV3 cells might be mediated by reduced STAT3 translation and activation." (PMID 37238935, 2023). "Furthermore, the interaction between CD96 and CD155 promotes stemness and chemoresistance in cancer cells by activating Src‐Stat3‐Opa1‐mediated mitochondrial membrane remodeling, which subsequently regulates fatty acid β‐oxidation." (PMID 36581470, 2023). "Similarly, the immune escape in cancer is associated with the activation of various pathways, such as WNT–β-catenin, MAPK, JAK/STAT3, and NF- κB signaling." (PMID 36982677, 2023).
cancer (continued). "Moreover, we identified MDSC secreted IL-6/IL-10/IL-1β induced STAT1/STAT3/NF-κβ signaling axis as a targeted cascade to promote early drug resistance in cancer cells." (PMID 38304256, 2023). "Additionally, the overexpression of ITGA2 activates the STAT3 signaling pathway, leading to the up-regulation of PD-L1 expression and promoting malignant tumor invasion." (PMID 37881431, 2023). "The JAK/STAT3 pathway has a key role in the growth and development of many human cancers." (PMID 37514090, 2023). "Therefore, RT-PCR was first carried out to detect the mRNA expression levels of STAT3 in indicated cancer cells." (PMID 36720310, 2023). "NFE2L2 and STAT3 are key pro-survival molecules, and thus, their targeting may represent a promising anti-cancer strategy." (PMID 37511362, 2023). "Thus, rational use of JAK inhibitors must be considered when treating STAT1 GOF or STAT3 GOF patients, in which the risk for viral and fungal infections or cancer is already elevated, respectively, in those patients." (PMID 37140667, 2023). "Our data confirmed the hypothesis related to IL-6 as a therapeutic target in cancer marked by STAT3 expression and cisplatin resistance." (PMID 36979673, 2023). "Since STAT3 can enhance cancer-stem-cell-like properties, erlotinib resistance may be associated with the enhanced cancer-stem-cell-like properties." (PMID 36834846, 2023). "STAT3 can behave as an oncogene and is expressed in approximately 70% of human cancers." (PMID 37511453, 2023). "Accordingly, compounds that can dysregulate STAT3 activation have huge therapeutic potential, and blocking the STAT3 signaling pathway may lead to cancer cell growth inhibition and apoptosis." (PMID 37397486, 2023). "STAT3 is involved in and contributes to 10 of the 14 recently updated hallmarks of cancer." (PMID 39872303, 2023). "Moreover, it was demonstrated that cytokines like IL-6 contribute to adipose wasting in patients with cancer through STAT3-dependent transcriptional changes that increase adipocyte lipolysis." (PMID 37481560, 2023). "In addition, in more than 75% of NPC tumors, STAT3 has been constitutively activated, directly contributing to the cancer’s invasiveness." (PMID 37375849, 2023). "Both compounds suppressed p-STAT3 levels in these cancer cell lines after 48 h." (PMID 37514107, 2023). "EJ could inhibit the function of STAT3 by binding to its DNA binding domain or promote STAT3 ubiquitination and degradation to reduce the STAT3 content in cancer cells." (PMID 37049904, 2023). "In addition, STAT3 has been shown to promote cell proliferative activity in several types of cancer stem cells." (PMID 36656267, 2023). "Therefore, targeting the STAT3 signaling pathway has been recognized as a promising therapeutic strategy for numerous cancers." (PMID 37724127, 2023). "Indeed, increased STAT3 activation is evident in various cancers including RCC where it is correlated with increased metastasis and poor patient outcomes." (PMID 38259453, 2023). "Chronic inflammation and cancer are mutually intertwined conditions, both driven by activation of common signaling pathways including signaling via nuclear factor kappa B (NF-kB), signal transducer and activator of transcription 3 (STAT3), and mammalian target of the rapamycin (mTOR)." (PMID 37020461, 2023). "However, aberrantly elevated STAT3 activity has been estimated to occur in more than 70% of human cancers." (PMID 37242454, 2023).
cancer (continued). "This would be consistent with the demonstrated NOT-elicited inhibition of JAK2 activation, and the documented roles of JAK2/STAT3 signaling in oncogenicity, maintenance of cancer stemness, cellular survival under stress, and resistance to multiple anticancer therapies." (PMID 37299411, 2023). "STAT3 has a long history of being studied as a target for anti-cancer therapeutics." (PMID 37073329, 2023). "Thus, agents that suppress the activation of Jak2 or Stat3 have potential in the prevention and treatment of cancer." (PMID 37089712, 2023). "As STAT3 is known to play an important role in promoting self-renewal of cancer stem cell enrichment and to give rise to tumorspheres, we performed a tumorsphere formation assay in vitro with HD-shSTAT3 and ONS-shSTAT3 cells grown in serum-free medium in ultra-low adherent tissue culture plates." (PMID 37190167, 2023). "STAT3 activation exacerbates TGF-β1-induced EMT through Smad3/Snail signaling in cancers." (PMID 38136312, 2023). "Stat3 is considered essential in embryonic stem cells and cancer stem cells." (PMID 37088831, 2023). "Future investigations should confirm the inhibitory effect of MHME and other Hispolon analogs on the STAT3 activity in a broad range of human cancers to address this speculation." (PMID 37893115, 2023). "The STAT3/HIF-1α signaling pathway exerts a promoting function in various cancers." (PMID 37628777, 2023). "Moreover, H19 is involved in the STAT3 pathway, which is critical for cancer aggressiveness, potentially impacting the tumor microenvironment." (PMID 37760852, 2023). "Additionally, polyphenolic compound resveratrol was demonstrated to induce the apoptosis of cancer cells by suppressing the phosphorylation of the Src-STAT3 signaling pathway." (PMID 36678599, 2023). "STAT3 is a central mediator of immunosuppression in the cancer microenvironment and its activation by cytokines, particularly IL-10, could mediate resistance to CAR-T cells." (PMID 37114129, 2023). "Additionally, it was reported that circNOLC1 contributed the improvement of cancer stem cell functions in BC through miR-365a-3p/STAT3 axis." (PMID 37626035, 2023). "Enhancement of the epithelial-mesenchymal transition through the activation of the JAK/STAT3 signaling pathway results in increased tumorigenic and metastatic potential, facilitates the transition of cancer stem cells, and contributes to chemoresistance in cancer." (PMID 37474926, 2023). "We next sought to determine whether STAT3 is a mediator accounting for cancer regulation of miR-26b-5p." (PMID 36737782, 2023). "STAT3 is a transcription factor that has been extensively studied in cancer." (PMID 37744063, 2023). "Moreover, STAT3 cooperates with NF-κB in IL-6 induction and the IL-6/STAT3 pathways synergize in the induction of c-MYC leading to promoting cancer cell survival." (PMID 37480115, 2023). "Thus, suppressing the EMT and STAT3 signal pathways is crucial for developing effective cancer therapies." (PMID 37755102, 2023). "In the TME, STAT3 is constitutively activated to induce cancer progression and immunosuppression." (PMID 37190158, 2023). "F. nucleatum may enhance the expression of cancer-related genes and oncogenes including STAT3, JAK1, and MYC." (PMID 37174014, 2023). "In other words, aberrant activation of STAT3 is involved in malignant phenotypes of cancers." (PMID 38017510, 2023). "However, STAT3 is aberrantly activated by increased phosphorylation in nearly 70% of human cancers, including brain tumors and MB." (PMID 37190167, 2023). "STAT3 can be activated in cancer cells in a constitutive or IL-6-induced manner." (PMID 37103357, 2023).
cancer (continued). "In conclusion, our study of clinical HNSCC cohorts showed that dysregulation of the c-MET/STAT3/AKT signaling pathway was linked to the development of HNSCC, as well as its worse prognoses, resistance to treatment, progression of cancer stem cell-like phenotypes, and resistance to certain drugs." (PMID 37373393, 2023). "Furthermore, it was observed that DLGAP5 also regulated the activity of the JAK2/STAT3 signaling pathway involved in cancer progression and development." (PMID 37958803, 2023). "DUET-02 (CpG-STAT3ASO) is a Signal Transducer and Activator of Transcription 3 (STAT3) antisense oligonucleotide (STAT3ASO) conjugated to immunostimulatory CpG oligodeoxynucleotides that is currently being explored for the treatment of cancer." (PMID 37475868, 2023). "In addition, STAT5a has overlapping functions with STAT3 protein in cancer development and progression." (PMID 37369132, 2023). "Follow-up pharmacodynamic experiments demonstrated that EJ significantly inhibited metastasis of cancer cells both in vitro and in vivo, and that the protein levels of STAT3, MMP-2, and MMP-9 could be dose-dependently reduced by EJ." (PMID 37049904, 2023). "Similarly, withaferin A inhibited the lung cancer spheroid-forming capacity and reduced the growth of cancer stem cells by decreasing the action of the mTOR/STAT3 signaling pathway." (PMID 37259311, 2023). "We further showed WZ26 effectively inhibited the activation of STAT3 in CCA cancer cells." (PMID 36647192, 2023). "Importantly, previous research has demonstrated that in cancer cells that have constitutively active B-Raf (V600E) activates downstream STAT3, which in turn activates Mcl1 transcription, which is an antiapoptotic factor." (PMID 37108645, 2023). "Moreover, specific asymmetric dimethylarginine antibody (R729me2a) was employed to measure STAT3’s R729me2a levels in cancer cells expressing Vector, PRMT6 WT, or PRMT6 KLA mutant." (PMID 37813837, 2023). "In cancer, sustained STAT3 activation occurs through several mechanisms, e.g., excessive cytokine and growth factor stimulation, hyper-activation or mutation of receptor/non-receptor associated kinases (JAK and Src family kinases), or loss of negative regulators (SOCS and PIAS proteins)." (PMID 37190167, 2023). "Additionally, SNHG14 enhances malignancy by upregulating STAT3 and increasing the proliferation and invasion of cancer cells through the downregulation of miR-613." (PMID 37760852, 2023). "Furthermore, compound calendula A has been verified to reduce p-STAT3 expression in various cancers, such as lung, breast, and liver types." (PMID 38202691, 2023). "In addition, crosstalk exists between TAMs and cancer cells in the TME, and IL-6 secreted by TAMs binds to the IL-6 receptor on the surface of cancer cells and phosphorylates STAT3 (pSTAT3)." (PMID 38074679, 2023). "In conclusion, we found that an active ingredient EJ in EL could act as a STAT3 degrader to inhibit cancer cell metastasis and would be a promising agent for cancer therapy." (PMID 37049904, 2023). "It has been revealed that extracellular ATP could induce STAT3 signaling and NF-κB pathway activation, which links inflammation to cancer and is related to the release of some chemokines and STC1." (PMID 37158903, 2023). "Herein, it was noted that STAT-3 expression was downregulated by vitamin B6 by 3.2-fold from 1.9-fold (LPS) to -1.2-fold (B6 + LPS) (p ≤ 0.005), indicating that this lowered expression would promote anti-cancer properties in vivo." (PMID 37761018, 2023). "Unregulated activation of STAT3 occurs in various cancers and contributes to tumorigenesis." (PMID 38203502, 2023). "Napabucasin inhibits cancer stemness mainly by inhibiting STAT3 and its target genes." (PMID 37570646, 2023). "Among them, STAT3 has been proven to be critically important for cancer progression." (PMID 37511611, 2023). "Similarly, pharmacological inhibition of STAT3 ameliorates muscle wasting in several mouse models of cancer cachexia." (PMID 37217930, 2023).